TOX4 (TOX high mobility group box family member 4)
Description:
Transcription factor that modulates cell fate reprogramming from the somatic state to the pluripotent and neuronal fate (By similarity). In liver, controls the expression of hormone-regulated gluconeogenic genes such as G6PC1 and PCK1 (By similarity). This regulation is independent of the insulin receptor activation (By similarity). Also acts as a regulatory component of protein phosphatase 1 (PP1) complexes. Component of the PNUTS-PP1 protein phosphatase complex, a PP1 complex that regulates RNA polymerase II transcription pause-release. PNUTS-PP1 also plays a role in the control of chromatin structure and cell cycle progression during the transition from mitosis into interphase.
Synonyms: C14orf92; KIAA0737; LCP1; MIG7
Tractability: PROTAC: ubiquitination databases record sites on it; its protein half-life has been measured.
Gene: Protein-coding gene on chromosome 14 (21,476,597 to 21,499,175, forward strand). Ensembl gene ENSG00000092203.
Subcellular location: Nucleus; Chromosome
Subcellular location (Human Protein Atlas): Nucleoplasm; Vesicles
Gene Ontology:
Molecular function: protein binding; chromatin DNA binding
Biological process: positive regulation of transcription elongation by RNA polymerase II; RNA polymerase II promoter clearance; regulation of transcription by RNA polymerase II
Cellular component: chromatin; chromosome, telomeric region; PTW/PP1 phosphatase complex; nucleus; chromosome
Genetic constraint (gnomAD): Loss-of-function variants: 12 observed, 62.48 expected, observed/expected ratio (o/e) 0.19, 90% interval 0.12 to 0.31. The upper end of that interval is the gene's LOEUF score, 0.31, which puts it in group 1 of 6, group 1 being the genes least tolerant of losing a copy. Missense variants: 495 observed, 776.14 expected, observed/expected ratio (o/e) 0.64, 90% interval 0.59 to 0.69. Synonymous variants: 268 observed, 280.97 expected, observed/expected ratio (o/e) 0.95, 90% interval 0.86 to 1.05.
Homologues: Orthologues: macaque TOX4 (99% identical), chimpanzee TOX4 (99% identical), dog TOX4 (98% identical), rabbit TOX4 (97% identical), guinea pig TOX4 (95% identical), mouse Tox4 (95% identical), rat Tox4 (95% identical), tropical clawed frog tox4 (65% identical), zebrafish tox4a (46% identical), zebrafish tox4b (41% identical), Caenorhabditis elegans hmg-4 (9% identical), Caenorhabditis elegans hmg-3 (8% identical). Paralogues in human: TOX3 (32% identical), TOX (29% identical), TOX2 (26% identical), SP100 (12% identical), SMARCE1 (12% identical), HMGXB4 (12% identical), UBTF (12% identical), SSRP1 (11% identical), SP140 (10% identical), SP110 (10% identical), HMG20B (9% identical), HMGB2 (9% identical), and 8 more.
Diseases named in the same sentence as TOX4 in open-access papers:
TOX4 is named in the same sentence as 20 diseases in open-access papers, as found by Europe PMC text mining. Sharing a sentence is not in itself a finding about the gene and the disease. The quoted sentences say what the papers report.
breast carcinoma (2 papers, 2012 to 2016). "One novel lncRNA, AC145110.1 on 8p12, was found differentially co-expressed with 127 mRNAs (including TOX4 and MAEL) in tumor and normal breast tissue and also highly correlated with breast cancer clinical outcomes." (PMID 27597120, 2016). "We found two breast cancer-related lncRNAs, MALAT1 and XIST, were significantly and differentially co-expressed with mRNAs (ALG14, TOX4, and C12orf32) in tumor and normal breast tissue via trans-acting mechanism." (PMID 27597120, 2016). "In contrast, the promoter CpG island of TOX4 was unmethylated in all lung and breast cancer cell lines, and none of these genes were methylated in normal tissue (NHBEC, HBEC, PBMC, and DNLT)." (PMID 22496870, 2012).
diabetes (2 papers, 2020 to 2024). "As Tox4 is expressed at higher levels in all studied tissues of NZO mice, it appears to be an important player in obesity and diabetes." (PMID 32350386, 2020).
glioma (2 papers, 2020 to 2023). A benign or malignant brain and spinal cord tumor that arises from glial cells (astrocytes, oligodendrocytes, ependymal cells). "Subsequently, we assessed the target proteins related to cell mobility and found that TOX4 (also known as MIG7) is associated with the invasion ability in glioma cells." (PMID 37726723, 2023). "The analysis of TOX protein family members showed coexpression of TOX, TOX2, TOX3, and TOX4 in pan-glioma analysis, LGG alone, and GBM alone." (PMID 32762688, 2020).
lung carcinoma (2 papers, 2022 to 2023). "In our study, we found that TOX4 knockdown severely reduced the migration and invasion of lung cancer cells; however, TOX4-overexpression enhanced cell migration and invasion." (PMID 37726723, 2023). "The evidence showed that NTSR1 is a novel and convergent downstream target of SLCO4A1-AS1/TOX4 and is involved in regulating SLCO4A1-AS1/TOX4-mediated migration and invasion in lung cancer cells." (PMID 37726723, 2023). "Immunohistochemistry of the resected lungs validated the role of TOX4 in the promotion of lung cancer metastasis in vivo." (PMID 37726723, 2023). "In summary, SLCO4A1-AS1 exerts its inhibitory influence on NTSR1 expression through its interaction with TOX4, thereby exerting a modulatory control over the migratory and invasive behaviors of lung cancer cells." (PMID 37726723, 2023). "We found that TOX4 was predominantly localized in the nuclei of lung cancer cells." (PMID 37726723, 2023). "In contrast, TOX4-overexpression augmented lung cancer cell migration and invasion." (PMID 37726723, 2023). "SLCO4A1-AS1 reverses TOX4/NTSR1-dependent migration and invasion and reduces lung cancer cell motility by remodeling the cytoskeleton." (PMID 37726723, 2023). "In this study, we have discovered that TOX4 directly binds to the NTSR1 promoter and enhances transcription of the NTSR1 gene in lung cancer cells." (PMID 37726723, 2023). "The regulatory network of SLCO4A1-AS1, TOX4, and NTSR1 in regulating cancer migration and invasion may provide potential anti-metastatic therapeutic targets for the treatment of lung cancer." (PMID 37726723, 2023). "In other types of cancer, such as breast and lung cancer, it was determined that TOX4 was highly expressed; however, it has not yet been linked to LLA." (PMID 36428851, 2022).
acute lymphocytic leukaemia (1 paper, 2024). "The METTL13 loci carried TOX high mobility group box family member 4 (TOX4) and spalt-like transcription factor 2 (SALL2) genes, and the expression of those genes was changed in the human acute lymphocytic leukaemia." (PMID 39596561, 2024).
head and neck cancer (1 paper, 2025). A primary or metastatic malignant neoplasm affecting the head and neck. "In head and neck cancer, the expression level of TOX4 correlated with adverse survival probability; similar patterns of association between TOX4 expression and shorter patient survival were also seen in stomach cancer, urothelial cancer, and pancreatic cancer." (PMID 40328361, 2025). "Clinical data illustrated the gene amplification and upregulation of TOX4 in various types of cancer, including head and neck cancer where TOX4 expression correlated with adverse patient survival." (PMID 40328361, 2025). "In line with its role in DNA repair, TOX4 emerges as a promising target for anticancer drug development, and its targeting enhances tumor cell sensitivity to DNA damage in head and neck cancer and other malignancies." (PMID 40328361, 2025). "Because the anchorage-independent growth potential constitutes a physiologically important feature of tumor cells, we studied the impact of TOX4 depletion on the growth and treatment response of head and neck cancer cells in anchorage-independent spheroid culture." (PMID 40328361, 2025).
HIV-1 infection (1 paper, 2013). The type species of lentivirus and the etiologic agent of acquired immunodeficiency syndrome (AIDS). "Our results obtained in TOX4 HMG expressing cells suggests that this domain could be involved during HIV-1 infection." (PMID 24312278, 2013). "What could be the role of TOX4 and NOVA1 during HIV-1 infection?" (PMID 24312278, 2013).
influenza (1 paper, 2019). An acute viral infection of the respiratory tract, occurring in isolated cases, in epidemics, or in pandemics; it is caused by serologically different strains of viruses (influenzaviruses) designated A, B, and C, has a 3-day incubation period, and usually lasts for 3 to 10 days. "To confirm the specificity of this 100 kDa band, we tagged the N- or C-terminus of TOX4 with human influenza hemagglutinin (HA) tags in mouse ESCs followed by western blot with anti-HA antibodies." (PMID 31519808, 2019).
lung adenocarcinoma (1 paper, 2023). A carcinoma that arises from the lung and is characterized by the presence of malignant glandular epithelial cells. "Moreover, survival analysis using the Kaplan–Meier plotter revealed that patients with lung adenocarcinoma who had higher TOX4-expressing tumors had shorter overall survival and recurrence than patients with lower TOX4-expressing tumors." (PMID 37726723, 2023).
sarcoma (1 paper, 2025). A usually aggressive malignant neoplasm of the soft tissue or bone. "Interestingly, our analysis of The Cancer Genome Atlas database uncovered amplification of TOX4 gene in 1 to 3% of various types of cancer, including those of ovary, stomach, lung, bladder, sarcoma, head and neck, brain, adrenal cortex, liver, and pancreas." (PMID 40328361, 2025).
cancer (10 papers, 2012 to 2025). A tumor composed of atypical neoplastic, often pleomorphic cells that invade other tissues. "This platinated distorted DNA is also a good substrate for other proteins, such as HMG-B4 and other transcription factors containing HMG-boxes such as SRY, LEF-1 or TOX4 that are associated with cancer stemness, and targets for cancer treatment." (PMID 29921764, 2018). "In this study, we demonstrated that SLCO4A1-AS1 participates in cancer cell migration and invasion by physically sequestering TOX4 and downregulating TOX4-dependent transcription." (PMID 37726723, 2023). "One interesting outcome of our work is that Tox4 may be relevant for the control of cell identity in regenerative medicine, human disorders and cancer therapy settings." (PMID 31519808, 2019). "Therefore, we speculate that TOX4 promotes cancer cell migration and invasion by regulating downstream genes involved in cell motility." (PMID 37726723, 2023). "Given that Tox4 is involved in cell fate changes, it will be interesting to test whether this can be harnessed to direct cell fate and whether it contributes to diseases including cancer." (PMID 31519808, 2019). "Functionally, NTSR1 promotes cancer cell migration and invasion through cytoskeletal remodeling, and knockdown of NTSR1 significantly inhibits TOX4-induced migration and invasion." (PMID 37726723, 2023). "Extension of these assays to TOX, TOX3, and TOX4 genes that share similar genomic structure and protein homology with TOX2 revealed distinct methylation profiles by smoking status, histology, and cancer type." (PMID 22496870, 2012). "Moreover, TOX4 regulates the cell cycle and fate, but there is no information regarding the expression characteristics of TOX4 in cancer or hematological malignancies." (PMID 34692519, 2021).
tumor (5 papers, 2015 to 2025). "Consistent with the function of TOX4 in DNA repair, our study showed that targeting TOX4 in conjunction with DNA-damaging drugs exhibited enhanced tumor cell responses." (PMID 40328361, 2025). "In particular, these genes are associated with more aggressive tumor phenotype (SAL2), migration and invasion (TOX4, PRMT5, AJUBA) development and progression (ZNF219, CEBPE)." (PMID 34944989, 2021).
infection (3 papers, 2013 to 2024). The state of being infected such as from the introduction of a foreign agent such as serum, vaccine, antigenic substance or organism. "Single round VSV-G pseudotyped infection by HIV-Luc and MLV luc was measured in 293T cells that stably express TOX4 PIR, TOX4 HMG, NOVA1 PIR or LEDGF IBD, fused to EGFP." (PMID 24312278, 2013).
TOX4 also shares sentences with these, for which no sentence is quoted: acute kidney injury (1 paper); esophageal cancer (1); hematological malignancies (1); melanoma (1); Obesity (1); pancreatic cancer (1); stomach cancer (1).